CAPRIN1 (cell cycle associated protein 1)
Description:
mRNA-binding protein that acts as a regulator of mRNAs transport, translation and/or stability, and which is involved in neurogenesis, synaptic plasticity in neurons and cell proliferation and migration in multiple cell types. Plays an essential role in cytoplasmic stress granule formation. Acts as an mRNA regulator by mediating formation of some phase-separated membraneless compartment: undergoes liquid-liquid phase separation upon binding to target mRNAs, leading to assemble mRNAs into cytoplasmic ribonucleoprotein granules that concentrate mRNAs with associated regulatory factors. Undergoes liquid-liquid phase separation following phosphorylation and interaction with FMR1, promoting formation of cytoplasmic ribonucleoprotein granules that concentrate mRNAs with factors that inhibit translation and mediate deadenylation of target mRNAs. In these cytoplasmic ribonucleoprotein granules, CAPRIN1 mediates recruitment of CNOT7 deadenylase, leading to mRNA deadenylation and degradation. Binds directly and selectively to MYC and CCND2 mRNAs. In neuronal cells, directly binds to several mRNAs associated with RNA granules, including BDNF, CAMK2A, CREB1, MAP2, NTRK2 mRNAs, as well as to GRIN1 and KPNB1 mRNAs, but not to rRNAs.
Synonyms: p137GPI; GPIAP1; GPIP137; M11S1; RNG105; caprin-1; CONDCAC; GRIP137; NEDLAAD
Tractability: PROTAC: ubiquitination databases record sites on it; its protein half-life has been measured.
Gene: Protein-coding gene on chromosome 11 (34,051,674 to 34,102,610, forward strand). Ensembl gene ENSG00000135387.
Subcellular location: Cytoplasm, Cytoplasmic ribonucleoprotein granule; Cytoplasm, cytosol; Cell projection, dendrite; Cell projection, lamellipodium
Subcellular location (Human Protein Atlas): Cytosol; Centriolar satellite; Centrosome
Gene Ontology:
Molecular function: ATP binding; molecular condensate scaffold activity; molecular function activator activity; mRNA binding; protein binding; RNA binding; signaling adaptor activity
Biological process: membraneless organelle assembly; negative regulation of translation; positive regulation of stress granule assembly; regulation of deadenylation-dependent decapping of nuclear-transcribed mRNA; positive regulation of dendrite morphogenesis; positive regulation of dendritic spine morphogenesis
Cellular component: cell leading edge; cytoplasm; cytoplasmic stress granule; cytosol; intracellular membraneless organelle; membrane; P-body; cytoplasmic ribonucleoprotein granule; dendrite; lamellipodium; synapse
Genetic constraint (gnomAD): Loss-of-function variants: 20 observed, 78.05 expected, observed/expected ratio (o/e) 0.26, 90% interval 0.18 to 0.37. The upper end of that interval is the gene's LOEUF score, 0.37, which puts it in group 1 of 6, group 1 being the genes least tolerant of losing a copy. Missense variants: 700 observed, 798.08 expected, observed/expected ratio (o/e) 0.88, 90% interval 0.82 to 0.93. Synonymous variants: 299 observed, 288.88 expected, observed/expected ratio (o/e) 1.03, 90% interval 0.94 to 1.14.
Gene-disease validity (ClinGen):
ClinGen rates the evidence that CAPRIN1 causes each of these diseases.
neurodegeneration, childhood-onset, with cerebellar ataxia and cognitive decline (autosomal dominant): Moderate.
neurodevelopmental disorder with language impairment, autism, and attention deficit-hyperactivity disorder (autosomal dominant): Moderate.
Homologues: Orthologues: chimpanzee CAPRIN1 (100% identical), macaque CAPRIN1 (100% identical), dog CAPRIN1 (99% identical), pig CAPRIN1 (98% identical), mouse Caprin1 (97% identical), rat Caprin1 (96% identical), guinea pig CAPRIN1 (95% identical), rabbit CAPRIN1 (91% identical), tropical clawed frog caprin1 (74% identical), zebrafish caprin1b (58% identical), zebrafish caprin1a (54% identical), Drosophila melanogaster Capr (27% identical). Paralogues in human: CAPRIN2 (35% identical).
Diseases named in the same sentence as CAPRIN1 in open-access papers:
CAPRIN1 is named in the same sentence as 57 diseases in open-access papers, as found by Europe PMC text mining. Sharing a sentence is not in itself a finding about the gene and the disease. The quoted sentences say what the papers report.
hepatocellular carcinoma (8 papers, 2018 to 2025). A malignant tumor that arises from hepatocytes. "A previous study showed that CAPRIN1 is associated with several types of cancers including hepatoma, osteosarcoma, gastric cancer, and breast cancer." (PMID 35571493, 2022). "Tan and colleagues reported that CAPRIN1 is highly expressed in hepatoma cancer tissues as compared to the adjacent normal tissues and is associated with poor survival rates in patients with hepatoma." (PMID 35571493, 2022). "Upregulation of caprin-1 is associated with poor prognosis in hepatocellular carcinoma." (PMID 30687106, 2018). "Specific examples in hepatocellular carcinoma (HCC) include circVAMP3 promoting the phase separation of CAPRIN1, inhibiting HCC proliferation and metastasis, and circRNA-YBX1 facilitating cytoskeletal remodeling via LLPS to attenuate liver cancer metastasis." (PMID 41335135, 2025). "In fact, it has been reported that Caprin-1 is involved in cell growth of MCF-7, HeLa, and hepatocellular carcinoma cells, and its suppression in B lymphocyte line DT40 resulted in a prolonged G1 phase and slower proliferation." (PMID 31861640, 2019).
breast carcinoma (7 papers, 2014 to 2023). "CAPRIN1 is closely associated with cancer cell cycle and cell proliferation, such as lymphocytes, human breast cancer cells, cervical cancer Hela cells." (PMID 34017855, 2021). "In breast cancer, miR-223 suppresses the proliferation and invasion of cancer cells by targeting cytoplasmic activation/proliferation-associated protein 1 (Caprin-1)." (PMID 25177699, 2014). "We generated a rabbit anti-CAPRIN-1 polyclonal antibody (pAb-1) and tested its binding to the surface membrane of four human breast cancer cell lines, using flow cytometry." (PMID 37082579, 2023). "Overall, miR-223 overexpression leads to decreased Caprin-1 expression, which in turn represses the proliferation and invasion of breast cancer cells." (PMID 35205115, 2022). "Caprin-1 deregulation then results in greater carcinogenesis in breast cancer cell lines, such as MDA-MB-231." (PMID 35205115, 2022). "Gong and colleagues reported that overexpression of CAPRIN1 promotes breast cancer cell proliferation and invasion." (PMID 35571493, 2022). "Expression of CAPRIN-1 could also be detected on cancer cells derived from a patient with breast cancer and PDAC cells cultured in sphere conditions, suggesting that CAPRIN-1 is also expressed in cells enriched for highly tumorigenic cancer stem cells." (PMID 37082579, 2023). "However, other antibodies, such as the anti-CAPRIN-1 antibodies mAb-1 to 6, did indeed bind to both CAPRIN-1 protein and the membrane surface of cancer cells such as BT-474 (breast cancer) and SW780 (bladder cancer)." (PMID 37082579, 2023). "In summary, miR-223 may suppress proliferation and invasion of breast cancer cells by directly targeting Caprin-1." (PMID 35205115, 2022). "Caprin-1 overexpression promotes proliferation and invasion of breast cancer cells." (PMID 35205115, 2022). "In addition, miR-223 has been report to regulate the proliferation and invasion of human breast cancer cells for targeting Caprin-1." (PMID 26055874, 2015). "Although CAPRIN-1 is reportedly an intracellular protein, antibody pAb-1 unexpectedly binds to the surface of all tested cancer cells, suggesting that CAPRIN-1 may be expressed on the surface of breast cancer cells." (PMID 37082579, 2023).
autism spectrum disorder (6 papers, 2016 to 2026). A spectrum of developmental disorders that includes autism, and Asperger syndrome. "Deficiency of CAPRIN1 has been linked to autism spectrum disorders and long-term memory impairment, while a specific missense mutation (P512L) has recently been implicated in early-onset ataxia and neurodegeneration." (PMID 40063661, 2025). "To date, CAPRIN1 has been associated with two conditions: increased CAPRIN1 expression has been connected to certain cancers, while its reduction has been linked with autism spectrum disorders and speech delay." (PMID 36136249, 2022). "Constitutive Caprin1 knockout in mice causes perinatal death and impairs the formation and maintenance of synapses and neuronal network, while CAPRIN1 deficiency has been associated with autism spectrum disorders (ASD) and long-term memory impairment." (PMID 36136249, 2022).
colon cancer (6 papers, 2017 to 2025). "This leads to increased caprin-1 production (miR-193a targets caprin-1 mRNA), disrupting the cell cycle and promoting cancer growth and metastasis in colon cancer cells." (PMID 40004027, 2025). "Caprin-1 is up-regulated in different cancer types, including lung, prostate, breast, gastric, liver and colon cancer." (PMID 36855123, 2023). "The impact of miR-193a overexpression on the inhibition of cell proliferation was further confirmed by the Caprin1 siRNA knockdown in CT26 colon cancer cells." (PMID 28211508, 2017). "Also, MVP-mediated exosomal sorting of miR-193a promotes colon cancer progression through targeting of Caprin1, which upregulates Ccnd2 and c-Myc." (PMID 31402975, 2019). "To determine whether miR-193a could target Caprin1 in colon cancer cells, we transfected the mature mouse miR-193a mimic into CT26 cells." (PMID 28211508, 2017).
gastric cancer (4 papers, 2018 to 2024). A primary or metastatic malignant neoplasm involving the stomach. "In another study, Lu and colleagues found that CAPRIN1 promotes cell proliferation, invasion and metastasis, whereas inhibition of CAPRIN1 suppresses the development of gastric cancer." (PMID 35571493, 2022). "In gastric cancer cells, a complex containing overexpressed circIPO7 blocks the caprin-1-G3BP1 interaction, dissociating caprin-1 and its target mRNAs (EGFR and mTOR) from the ribosome, leading to inhibition of their translation and consequent inactivation of the PI3K/AKT/mTOR pathway." (PMID 38778089, 2024).
Ataxia (3 papers, 2022 to 2026). Ataxia refers to impaired coordination of voluntary muscle movement. "In conclusion, we identify with the P512L mutation a highly critical domain in CAPRIN1, the alteration of which associates with early-onset ataxia and intellectual disability, thereby associating another PrLD-containing protein to a novel neurodegenerative disorder." (PMID 36136249, 2022). "This novel variant is consistent with the most common identified CAPRIN1 mutations, and his phenotypic presentation included the most common symptoms reported with CAPRIN1 mutations, including language impairment and speech delay, ADHD, ASD, respiratory symptoms, as well as ataxia." (PMID 41859620, 2026).
viral infection (3 papers, 2014 to 2024). "The antiviral effect was not restricted to the laboratory adapted DENV-2 NGC as G3BP1, G3BP2 and CAPRIN1 had antiviral activity against the clinical DENV-2 isolate PR1940 as well as the related yellow fever vaccine strain (YFV-17D)." (PMID 24992036, 2014). "Additionally, as a nucleating protein of SGs, G3BP1 binds mRNAs, 40S ribosomal subunits, initiation factors (eIF2, eIF3, eIF4), and RNA-binding proteins (e.g., poly(A) binding protein, Caprin1) for SGs assembly and protein translation arrest after viral infection." (PMID 39638802, 2024). "The various roles of Caprin-1 in cancer as a cell cycle regulator and in neurodegenerative disease as potential contributor to altered RNA metabolism and also the roles of G3BP in viral infections, cancer and neurodegenerative disease highlight the importance of this interaction." (PMID 37161291, 2023).
attention deficit-hyperactivity disorder (2 papers, 2021 to 2022). A disorder characterized by a marked pattern of inattention and/or hyperactivity-impulsivity that is inconsistent with developmental level and clearly interferes with functioning in at least two settings (e.g. at home and at school). "Furthermore, the gain-of-function model is in accordance with the increasing evidence that, conversely, CAPRIN1 reduction (e.g. haploinsufficiency) causes a different phenotype, characterized by language impairment, attention-deficit/hyperactivity disorder." (PMID 36136249, 2022).
clear cell renal cell carcinoma (2 papers, 2015). "Collectively, these data suggest that miR-1 directly suppresses CDK4, CDK6, Caprin1 and Slug expression in clear cell renal cell carcinoma." (PMID 26036633, 2015). "In renal cell clear cell carcinoma, the miR-1 targeted and regulated cell cycle proteins such as CDK4, CDK6, Caprin1 and Slug." (PMID 26807210, 2015).
colorectal cancer (2 papers, 2022 to 2023). A primary or metastatic malignant neoplasm that affects the colon or rectum. "In colorectal cancer, it has been reported that miR-193a can cause tumor cell cycle abnormalities and inhibit cell proliferation by targeting CAPRIN1." (PMID 36515758, 2022). "The analysis of cells derived from patients with gastric and colorectal cancer demonstrated that CAPRIN-1 was strongly expressed on virtually all cell membrane surfaces." (PMID 37082579, 2023).
esophageal squamous cell carcinoma (2 papers, 2022 to 2023). Esophageal squamous cell carcinoma (ESCC) is a type of esophageal carcinoma (EC) that can affect any part of the esophagus, but is usually located in the upper or middle third. "We observed high CAPRIN1 levels in several ESCA cell lines, especially in KYSE30 and KYSE70, compared with fibroblast cultured from esophageal squamous cell carcinoma tissue using the GEO database (GSE63941)." (PMID 36855123, 2023).
fragile X syndrome (2 papers, 2012 to 2022). A genetic syndrome caused by mutations in the FMR1 gene which is responsible for the expression of the fragile X mental retardation 1 protein. "As the world of RNA-binding proteins is expanding, understanding the role of Caprin1 and of other RNA-binding FMRP interactors, will be essential to unravel the functions altered by lack of FMR1 expression in the fragile X syndrome." (PMID 22737234, 2012).
hearing loss (2 papers, 2022 to 2026). "In summary, the data suggest a key role for Caprin1 acting pre- or post-synaptically to determine how the auditory system responds to and recovers from damage, revealing a potential therapeutic avenue for preventing acquired hearing loss." (PMID 35165318, 2022).
nasopharyngeal carcinoma (2 papers, 2022 to 2025). A carcinoma arising from the nasopharyngeal epithelium. "We demonstrated that CAPRIN1, an RNA-binding proteins associated with stress granule formation, as a potential target for nasopharyngeal carcinoma." (PMID 36515758, 2022). "CAPRIN1 was significantly upregulated in nasopharyngeal carcinoma cells and tissues." (PMID 36515758, 2022). "To characterize the functions of CAPRIN1 in NPC, we investigated the expression of CAPRIN1 in nasopharyngeal carcinoma cell lines and tissues." (PMID 36515758, 2022).
osteosarcoma (2 papers, 2021 to 2022). A usually aggressive malignant bone-forming mesenchymal neoplasm, predominantly affecting adolescents and young adults. "Another study performed by Sabile and colleagues found that CAPRIN1 promotes the development of osteosarcoma by interacting with extracellular matrix protein." (PMID 35571493, 2022).
ovarian carcinoma (2 papers, 2023 to 2025). A malignant neoplasm originating from the surface ovarian epithelium. ",56,57SNHG8 can combine with cell cycle-associated protein 1 (CAPRIN1) to influence the Wnt/β-catenin pathway, promoting the proliferation, migration, and EMT of ovarian cancer cells and suppressing cell apoptosis and stemness." (PMID 41200835, 2025). "We found that CAPRIN-1 was expressed on the membrane surface of most cancer cell lines and some cell lines, such as TOV-21G (ovarian cancer) and A-375 (melanoma), were negative, although there were not so many negative cancer cell lines." (PMID 37082579, 2023).
pancreatic cancer (2 papers, 2023). "We found that knockdown of Caprin-1 decreased accumulation of autophagosomes in mRFP-GFP-LC3 assay, suggesting that deficiency of Caprin-1 blocked autophagy flux in pancreatic cancer cells." (PMID 38082307, 2023). "We further corroborated high level expression of CAPRIN-1 on pancreatic cancer stem cells using autofluorescence as a distinct method for detecting cancer stem cells with high accuracy in primary cancer cells." (PMID 37082579, 2023). "Caprin-1 was upregulated in most of pancreatic cancer cell lines except CFPAC." (PMID 38082307, 2023). "Gene signatures and biological processes associated with advanced cancer and unfavorable outcome were profiled using bulk RNA sequencing and spatial transcriptome sequencing, Caprin-1 was identified as an oncogenesis to expedite pancreatic cancer growth by activating autophagy." (PMID 38082307, 2023). "Therefore, we were particularly intrigued to find that CD133+ cancer stem cells derived from patients with pancreatic cancer also strongly express CAPRIN-1 on the cell surface." (PMID 37082579, 2023). "The interaction between Caprin-1 and STK38 in pancreatic cancer cells were then confirmed." (PMID 38082307, 2023).